LINC00488 (long independently transcribed non-coding RNA 488)
Synonyms: FLJ41232; C3orf66
Gene: Long non-coding RNA gene on chromosome 3 (109,178,060 to 109,216,965, forward strand). Ensembl gene ENSG00000214381.
Diseases named in the same sentence as LINC00488 in open-access papers:
LINC00488 is named in the same sentence as 2 diseases in open-access papers, as found by Europe PMC text mining. Sharing a sentence is not in itself a finding about the gene and the disease. The quoted sentences say what the papers report.
thyroid cancer (1 paper, 2021). "Hence, the main objective of the study was to decipher the roles of LINC00488-miR-376a-3p-PON2 pathways in thyroid cancer, thereby providing a deep understanding of the LINC00488’s function in thyroid cancer to develop it as a promising diagnostic and therapeutic target for this disease." (PMID 33600548, 2021). "Nevertheless, to date, the functional role of LINC00488 in the progression of thyroid cancer is unclear." (PMID 33600548, 2021). "Our findings revealed that LINC00488 was highly expressed in thyroid cancer cell lines and knockdown of LINC00488 inhibited the cell proliferation, migration and invasion and promoted the cell apoptosis in thyroid cancer cell lines." (PMID 33600548, 2021). "Mechanistically, LINC00488 served as oncogenic gene in thyroid cancer progression through regulation of miR-376a-3p/PON2 axis." (PMID 33600548, 2021).
cancer (1 paper, 2021). A tumor composed of atypical neoplastic, often pleomorphic cells that invade other tissues. "Indeed, LINC00488 has been reported to sponge a mass of miRNAs in a variety of cancers." (PMID 33600548, 2021).